KRAS (KRas proto-oncogene, GTPase)
Diseases named in the same sentence as KRAS in open-access papers (continued):
Sharing a sentence is not in itself a finding about the gene and the disease.
lung cancer (continued). "In KRAS-mutant lung cancers and colon cancer, MEK inhibition can activate the MAP2K4-JNK-JUN feedback loop, leading to activation, especially of ERBB3 and FGFR1, which can reactivate MEK and AKT signaling." (PMID 40805153, 2025). "KRAS inhibitors have commonly been investigated for their potential role as chemotherapeutic agents, primarily against colorectal and lung cancers, due to their ability to promote Type I IFN and STING pathway expression." (PMID 40400715, 2025). "In KRAS-driven lung cancer, IL-10 and BMP2 in the SASP can act on vascular endothelial cells to promote angiogenesis." (PMID 39781471, 2025). "Kirsten rat sarcoma viral oncogene homolog (KRAS) mutations are associated with poor prognosis and poor response to standard therapeutic regimens in patients with nonsmall cell lung cancer (NSCLC)." (PMID 39992860, 2025). "In a model of KRAS-driven lung cancer, HK2 is transcriptionally activated by the transcription factor BACH1, which is stabilized by antioxidant treatment, triggering metastatic spread favored by glycolytic metabolism in cancer cells." (PMID 40734168, 2025). "A therapeutic study of mRNA similarly encoding multiple KRAS variants increased tumor-infiltration of CD8+ T cells and significantly delayed tumor growth in the syngeneic KRAS G12C-expressing lung cancer LL/2-bearing mice." (PMID 41012179, 2025). "Lung cancer cells with KRAS/MYC cooperation exhibited more pronounced proliferation and aggressiveness, as well as suppressive and inflammatory features of the immune microenvironment, compared to KRASG12D mutations alone." (PMID 41184283, 2025). "Combination of multipeptide KRAS vaccine and cholesterol metabolism inhibition enhanced the efficacy of vaccine in KRAS-driven lung cancer mouse models." (PMID 40437549, 2025). "Allele-specific inhibitors, which covalently bind to and trap KRAS G12C in an inactive state, have demonstrated clinical benefits in patients with lung cancer." (PMID 40970755, 2025). "In KRAS-mutant lung cancer, senescent macrophages secrete CCL2 to recruit MDSCs, while IL-10 and TGF-β polarize tumor-associated macrophages (TAMs) toward an immunosuppressive M2 phenotype, crippling cytotoxic T cell activity." (PMID 40510156, 2025). "In summary, we confirmed a strong synergistic effect between WEE1 inhibitors (WEE1i) and KRAS G12C inhibitors (G12Ci) in KRAS G12C-mutant lung cancer, driven primarily by the MYBL2–RRM2 axis." (PMID 40885709, 2025). "The transcription factors Snai1 and Twist1, both working as key regulators of epithelial-mesenchymal transition (EMT), are implicated in upregulating HBP enzymes, especially GFPT2, in KRAS-mutant lung cancer." (PMID 40830088, 2025). "Cong performed a study using a CRE-inducible KRASLSLG12D mouse model, which revealed a significant reduction in NK cell population and an increase in glycolysis during various stages of KRAS-driven lung cancer." (PMID 39806421, 2025). "The ERK/JNK signaling is more significantly activated, resulting in lower levels of DNA damage in KRAS-mutant lung cancer cells compared with KRAS WT lung cancer cells from patients." (PMID 39960727, 2025). "This cascade induces hypermethylation and high expression of CBS, consequently triggering cysteine production and maintaining antioxidative homeostasis, which is essential for the survival of KRAS-driven lung cancer cells." (PMID 40885716, 2025). "ERK3 is a well-established bona fide tumour-promoting gene in lung cancer, particularly in association with PTEN deletion and KRAS mutation, and its overexpression in patient samples correlates poorly with patient survival." (PMID 40936697, 2025).
lung cancer (continued). "In KRAS-mutant lung cancer with LKB1 deletion, Wnt signaling plays a role in maintaining the adenocarcinoma state by activating NKX2-1." (PMID 40568576, 2025). "Whole genome sequencing enables the simultaneous screening of multiple lung cancer driver genes, such as KRAS G12C, with 88% of these genes exhibiting a detection sensitivity exceeding 99%." (PMID 40949724, 2025). "We described before that LDHB is required for plasma membrane-localized SLC7A11-mediated glutathione metabolism in the tested KRAS-mutant lung cancer cells." (PMID 40090955, 2025). "Targeted therapy is an important method in the treatment of lung cancer, especially in the detection of common NSCLC mutations such as epidermal growth factor receptor (EGFR), rat sarcoma viral oncogene (KRAS), anaplastic lymphoma kinase (ALK), and BRAF genes." (PMID 39962757, 2025). "To elucidate the expression profiles of these genes in lung cancer tissues, we visualized the expression patterns of KRAS and ERBB2, revealing high expression in tumor regions." (PMID 39830364, 2025). "We and other groups previously showed the importance of co‐occurring mutated genes in modulating the pathobiology and therapy response of KRAS‐mutant lung cancer." (PMID 41025426, 2025). "Consistent with this, TBK1 promotes anti-apoptotic signaling by activating the NF-κB signaling pathway, which also plays a crucial role in the survival of KRAS-mutant lung cancer cells." (PMID 40076567, 2025). "Svensson reported that chronic treatment with ND-646 (ACC inhibitor) remarkedly dampens KRAS-driven lung cancer." (PMID 39806421, 2025). "Consistently, ALKBH5 PTMs, including phosphorylation and SUMOylation, are much more abundant in KRAS-mutant primary lung cancer cells compared with KRAS WT cells." (PMID 39960727, 2025). "In summary, fibroblasts emerged as a key source of immune regulatory signals, and a potential therapeutic target for improving the efficacy of KRAS inhibitors in lung cancer." (PMID 39782689, 2025). "This study adopts a structure-guided and expression-validated approach to characterize EGFR, ALK, KRAS, and PD-1—four of the most clinically actionable targets in lung cancer." (PMID 40927719, 2025). "Given DDX3X role as a crucial RNA-binding protein governing various aspects of gene expression, our study in KRAS-driven lung cancer cells revealed that DDX3X influences CBS translation without affecting transcription or mRNA stability." (PMID 40885716, 2025). "In summary, our findings lend mechanistic insight to the extrinsic signaling consequences of oncogenic KRAS in lung cancer." (PMID 39782689, 2025). "Nevertheless, our data are supportive of targeting BACE1 in KRAS driven lung cancers which also have a strong predilection to end up in the brain." (PMID 40601773, 2025). "Oncogenic mutations in the Ras gene, particularly in isoforms such as KRAS, HRAS, and NRAS, have been identified in different types of human cancers, including colorectal, pancreatic, and lung cancers." (PMID 40483365, 2025). "Westcott and his colleagues recorded the mutational landscapes of KRAS driven lung cancer, knockdown of MTUS1 expedited growth in a mouse lung cancer cell line caused by KRAS G12D79." (PMID 41203700, 2025).
lung cancer (continued). "The amplification of KRAS also renders lung cancer cells resistant to crizotinib, a MET inhibitor, by hypersensitizing them to ligand stimulation." (PMID 40312750, 2025). "Inhibitors of activated KRAS-mutant KRASG12C proved to be beneficial in lung cancer, including heavily pretreated patients." (PMID 41465386, 2025). "Here we show that aging represses oncogenic KRAS-driven tumor initiation and growth in genetically engineered mouse models of human lung cancer." (PMID 41188600, 2025). "Although the number of fibroblasts in the human samples was limited, we corroborated some in vitro data, including increased expression of CXCL1 in the KRASG12D-driven versus non–KRAS-driven lung cancer samples." (PMID 39782689, 2025). "To confirm that VVD-699 disrupts the RAS-p110α interaction in cells, we initially focused on KRAS mutant expressing H358 human lung cancer cells, which rely on KRASGly12Cys for maximal PI3K activation." (PMID 41066541, 2025). "Commonly displaying KRAS mutations, especially KRAS G12D and G12V which promote constitutive activation of the RAS-RAF-MEK-ERK signaling cascade are pancreatic, colorectal, and lung cancers." (PMID 40430848, 2025). "Within lung cancer, the retrospective IMMUNOTARGET registry showed that KRAS mutations were associated with improved response to ICI compared to other oncogenic mutations." (PMID 40362630, 2025). "In a KRAS-driven lung cancer model, the SASP secreted by senescent macrophages includes chemokines such as CCL2, CCL8, CCL7, CCL24, and CXCL13, which are involved in tumor cell metastasis." (PMID 39781471, 2025). "A prior investigation reported that highly p16‐expressing macrophage ablation by ABT‐737 decreased tumor burden by promoting immunosurveillance in a KRAS‐driven lung cancer model." (PMID 40624910, 2025). "This role of GATAD2B in CSCs aligns with the reported role of GATAD2B in promoting metastasis in KRAS-mutant lung cancer, strengthening the role of GATAD2B in cancer." (PMID 40136647, 2025). "In this study, we present evidence that the loss of DDX3X significantly delays tumor progression in various KRAS-driven lung cancer models." (PMID 40885716, 2025). "Consistently, high Bok and low TRIM28 levels correlate with increased survival in cancers like HCC and kidney cancer, further supporting Bok’s role as a tumor suppressor despite its pro-tumorigenic role in KRAS-driven lung cancer." (PMID 40841912, 2025). "In lung cancer patients, EBC analysis has revealed a greater number of detectable mutations in key oncogenes such as EGFR, KRAS, and PIK3CA compared to matched tumor tissue samples." (PMID 41373464, 2025). "This suggests that radon exposure closely affects tumor progression in KRAS-driven lung cancer models." (PMID 40725119, 2025). "We have previously demonstrated that inhibition of PP2A, through mutation or siRNA-mediated knockdown of PP2A-Aα, contributes to MEK1/2 inhibitor resistance in KRAS-mutant colon and lung cancers." (PMID 41086023, 2025). "While studying the response of KRAS-mutant lung cancer models to KRASG12C or MEK inhibitors combined with BH3 mimetics, we unexpectedly observed an association between the presence of STK11 mutations and dependence on MCL-1." (PMID 40316540, 2025). "To validate MYBL2-mediated transcriptional regulation of RRM2 in KRAS G12C mutant lung cancer, we identified two putative MYBL2-binding motifs within the predicted RRM2 promoter region (-2000 to +60)." (PMID 40885709, 2025).
lung cancer (continued). "Glecirasib’s notable efficacy in an intracranial tumor model suggests its potential for treating KRAS G12C–driven lung cancer with brain metastasis." (PMID 40304209, 2025). "Specific cancer-related gene sets, including PCa down-regulation, lung cancer with KRAS down-regulation, and breast cancer luminal versus basal down-regulation, were highlighted." (PMID 40356901, 2025). "In the KRAS-driven lung squamous cancer, enforced expression of SOX2 and/or loss of NKX2-1 leads to an increased TANs and promotes lung cancer tumorigenesis." (PMID 39806421, 2025). "Recent studies have shown that in KRAS-mutant lung cancer cells, YAP1 was the major driver of global RNA expression profile changes caused by LKB1 loss revealing a potential target." (PMID 40611261, 2025). "Chemokine-driven immunosuppression is exemplified in KRAS-mutant lung cancer, where senescent cells recruit MDSCs and regulatory Tregs via CCL2 secretion, establishing an immune-privileged niche." (PMID 40510156, 2025). "In our study, the average patient age was 66.4, consistent with previous reports indicating an average age range of 64–66 for KRAS mutant lung cancers." (PMID 39996842, 2025). "For instance, skewness has been linked with KRAS mutations in NSCLC, which are indicative of treatment resistance and poorly diagnosis of lung cancers." (PMID 41071045, 2025). "Recent studies reveal that antioxidants such as NAC, vitamin C, and vitamin E can stimulate angiogenesis during KRAS-driven lung cancer progression." (PMID 40646353, 2025). "Overall, combining these two drugs for treating KRAS G12C-mutant lung cancer is feasible and promising." (PMID 40885709, 2025). "This indicates that radiomics models can effectively distinguish the KRAS status in lung cancer patients." (PMID 41584578, 2025). "To assess the clinical relevance of our findings in the KRAS inducible and reversible lung adenocarcinoma mouse model, we used a publicly available scRNA-seq dataset of KRASG12D-driven and non–KRAS-driven lung cancer." (PMID 39782689, 2025). "We present the screening and functional studies that identified FGFR1 activation as a feedback mechanism following KRAS G12C inhibition in lung cancer cells with a mesenchymal phenotype." (PMID 40788860, 2025). "It has been reported that the IL-1β monoclonal antibody, canakinumab significantly reduces lung cancer incidence and mortality by inhibiting inflammation in KRAS-mutant NSCLC." (PMID 41184283, 2025). "In lung cancer and PDAC, KRAS mutations can directly induce interleukin-8 production and secretion by tumour cells, thus triggering endothelial cell recruitment, tumour-associated inflammation and angiogenesis." (PMID 39820726, 2025). "To investigate the oncogenic relevance of REGγ in KRAS-mutant cancers, we obtained isogenic human colon and lung cancer cells (HCT8, H661, HPNE, and H522) through the introduction of the constitutively active KRASG13D mutation." (PMID 40091835, 2025). "This study also represents the instance of a mutant KRAS oncogene hijacking the ALKBH5 PTMs/m6A methylation–mediated DNA damage response pathway to confer resistance to cytotoxic drugs in lung cancer cells." (PMID 39960727, 2025). "Success with the use of the novel KRAS inhibitor Sotorasib in lung cancer patients and colon cancer patients with cancers harbouring specifically G12C mutant KRAS protein has raised hope for similar treatments for PDAC." (PMID 40723241, 2025). "The effectiveness of RAS/MAPK inhibitors in treating metastatic KRAS-mutant non–small cell lung cancer (NSCLC) is often hindered by the development of resistance driven by disrupted negative feedback mechanisms led by phosphatases like PP2A." (PMID 41086023, 2025).
lung cancer (continued). "Lung cancer development was almost completely suppressed when CA170 was used in combination with a KRAS peptide vaccine in a carcinogen induced lung cancer mouse model." (PMID 40437549, 2025). "This large cohort study contains mutational data for KRAS, KEAP1 and NFE2L2 from 853 lung cancer patients." (PMID 40890297, 2025). "Daraxonrasib halts growth of KRAS-addicted lung cancer and colon cancer cells; however, its efficacy and mechanisms of action in bone cancers have not been evaluated." (PMID 40779492, 2025). "Sotorasib was the first clinically approved KRAS G12 C inhibitor, which was shown to prolong PFS in previously treated G12 C-mutated lung cancers." (PMID 40524071, 2025). "To study the extrinsic role of oncogenic KRAS in lung cancer maintenance and progression, we modified a GEMM that expresses mutant KRASG12D in an inducible and reversible manner in the lung epithelium." (PMID 39782689, 2025). "Key findings demonstrated correlations between PET-derived radiomic features and genomic alterations, such as KRAS, EGFR, and TGFβ mutations in lung cancer, and prognostic biomarkers in other malignancies." (PMID 40192792, 2025). "In KRAS-driven lung cancer, inactivation of NSD2 by the oncohistone H3K36M leads to activation of an antiviral-like immune response through SETD2-mediated H3K36me3 deposition." (PMID 41301842, 2025). "Previous studies demonstrated that combining 5Z-7-Oxozeaenol with hyperthermia (HT) enhanced cell death in KRAS-mutant A549 lung cancer cells in a dose-dependent manner." (PMID 41295383, 2025). "Certain types of cancer (e.g., lung cancer, KRAS wild-type pancreatic cancer) have relatively high frequencies of gene fusions and should be prioritized for comprehensive genomic profiling." (PMID 40223139, 2025). "Subsequent studies identified cancer-associated genetic alterations in cfDNA from the plasma of cancer patients, such as KRAS mutations in pancreatic cancer and EGFR mutations in lung cancer." (PMID 40385463, 2025). "Differential expression analysis of epithelial cells showed a significant increase in expression of CXCL1, CXCL2, and HDGF in KRASG12D-driven lung cancer samples compared with non–KRAS-driven lung cancer." (PMID 39782689, 2025). "In our study, by utilizing a spontaneous KRAS-driven lung cancer model, human lung cancer organoids, and cell lines, we have unveiled a pivotal role of DDX3X in lung cancer progression." (PMID 40885716, 2025). "In summary, our analysis demonstrates that SHP2 expression emerges as a promising prognostic biomarker specifically in KRAS mutant lung cancer subgroups." (PMID 39992860, 2025). "In lung cancer, suppression of inflammation genes has been reported in patients harboring STK11 and KRAS co-mutations." (PMID 41051525, 2025). "In conclusion, our findings elucidate the critical function of DDX3X in maintaining antioxidant homeostasis and provide an alternative strategy to treat KRAS-driven lung cancer." (PMID 40885716, 2025). "We subsequently developed RLY01, a REGγ-proteasome inhibitor that effectively suppressed tumor growth in KRAS-mutant cancer models and lung cancer organoids." (PMID 40091835, 2025). "FASN activated by ERK alters lipid signatures and accelerates the proliferation of KRAS-positive lung cancer cells." (PMID 41184283, 2025). "AmoyDx Lung Cancer Multi-Gene PCR Panel showed KRAS non-G12C positivity, and PD-L1 expression assessed by 22C3 immunohistochemistry showed TPS 40%." (PMID 40161114, 2025). "Sotorasib, a novel small molecule inhibitor targeting KRAS/G12C, has emerged as a promising therapeutic option for KRAS G12C-positive nonsmall cell lung cancer." (PMID 40286847, 2025). "Analysis of TCGA data revealed significantly higher E2F1 expression in KRAS‐mutant lung cancer patients compared to those with wild‐type KRAS." (PMID 40936169, 2025).